RFNG (RFNG O-fucosylpeptide 3-beta-N-acetylglucosaminyltransferase)
Description:
Glycosyltransferase that initiates the elongation of O-linked fucose residues attached to EGF-like repeats in the extracellular domain of Notch molecules. Modulates NOTCH1 activity by modifying O-fucose residues at specific EGF-like domains resulting in enhancement of NOTCH1 activation by DLL1 and JAG1. May be involved in limb formation and in neurogenesis.
Tractability: Antibody: UniProt predicts a signal peptide or a membrane-spanning region. PROTAC: ubiquitination databases record sites on it.
Gene: Protein-coding gene on chromosome 17 (82,047,902 to 82,051,831, reverse strand). Ensembl gene ENSG00000169733.
Subcellular location: Golgi apparatus membrane
Subcellular location (Human Protein Atlas): Nucleoplasm
Pathways (Reactome):
Signal Transduction: Pre-NOTCH Processing in Golgi
Gene Ontology:
Molecular function: O-fucosylpeptide 3-beta-N-acetylglucosaminyltransferase activity; glycosyltransferase activity
Biological process: animal organ morphogenesis; regulation of Notch signaling pathway; pattern specification process
Cellular component: extracellular region; Golgi membrane; membrane
Genetic constraint (gnomAD): Loss-of-function variants: 37 observed, 26.97 expected, observed/expected ratio (o/e) 1.37, 90% interval 1.05 to 1.78. The synonymous counts are far from expectation, so gnomAD's model fits this gene poorly and the ratio says little. Missense variants: 492 observed, 376.86 expected, observed/expected ratio (o/e) 1.31, 90% interval 1.21 to 1.41. Synonymous variants: 252 observed, 154.5 expected, observed/expected ratio (o/e) 1.63, 90% interval 1.47 to 1.81.
Homologues: Orthologues: chimpanzee RFNG (99% identical), pig RFNG (89% identical), dog RFNG (88% identical), guinea pig RFNG (85% identical), macaque RFNG (81% identical), rat Rfng (81% identical), mouse Rfng (81% identical), zebrafish rfng (63% identical), tropical clawed frog rfng (58% identical), Drosophila melanogaster fng (42% identical). Paralogues in human: LFNG (60% identical), MFNG (50% identical), B3GLCT (21% identical).
Diseases named in the same sentence as RFNG in open-access papers:
RFNG is named in the same sentence as 9 diseases in open-access papers, as found by Europe PMC text mining. Sharing a sentence is not in itself a finding about the gene and the disease. The quoted sentences say what the papers report.
adrenocortical carcinoma (1 paper, 2023). "On the other hand, high expression of RFNG was significantly associated with poor prognosis in patients with adrenocortical carcinoma (ACC) and KIRC." (PMID 37932706, 2023).
colon adenocarcinoma (1 paper, 2024). "We analyzed the information on RFNG expression in colon adenocarcinoma (COAD) and rectal adenocarcinoma (READ) from The Cancer Genome Atlas (TCGA) database and found that RFNG mRNA levels were much higher in tumor tissues than in normal tissues." (PMID 39120977, 2024).
cancer (3 papers, 2014 to 2024). A tumor composed of atypical neoplastic, often pleomorphic cells that invade other tissues. "High expression of RFNG is also a risk factor in some cancer types, while low expression can also predict poor prognosis in certain tumors." (PMID 37932706, 2023). "In conclusion, our pan-cancer analyses have revealed correlations between LFNG, MFNG, and RFNG expressions, with its methylation states, mutations, clinical prognosis, and immune cell infiltration." (PMID 37932706, 2023).
tumor (2 papers, 2023 to 2024). "At the same time, RFNG gene is involved in the degradation, transport and repair processes of tumor cells to chemotherapy drugs, and mutation or deletion may lead to the abnormality of these processes, making tumor cells resistant to chemotherapy drugs." (PMID 37932706, 2023). "We further performed quantitative PCR (qPCR), immunoblotting, and immunohistochemistry (IHC) analyses and observed a notable increase in RFNG expression in tumor tissues compared to paired normal tissues." (PMID 39120977, 2024).
RFNG also shares sentences with these, for which no sentence is quoted: aortic stenosis (1 paper); breast carcinoma (1); lung carcinoma (1); pancreatic cancer (1); rectal adenocarcinoma (1).